ENSG00000288796 (novel protein)
Gene: Protein-coding gene on chromosome 4 (73,981,074 to 73,988,190, reverse strand). Ensembl gene ENSG00000288796.
Genetic constraint (gnomAD): Loss-of-function variants: 19 observed, 18.48 expected, observed/expected ratio (o/e) 1.03, 90% interval 0.72 to 1.51. Missense variants: 228 observed, 233.88 expected, observed/expected ratio (o/e) 0.97, 90% interval 0.87 to 1.09. Synonymous variants: 95 observed, 94.29 expected, observed/expected ratio (o/e) 1.01, 90% interval 0.85 to 1.2.